CYLD (CYLD lysine 63 deubiquitinase)
Diseases named in the same sentence as CYLD in open-access papers (continued):
Sharing a sentence is not in itself a finding about the gene and the disease.
lung carcinoma (16 papers, 2016 to 2024). "Inhibition of CYLD increased resistance to apoptosis by activating NF-kappaB, suggesting a mechanism through which loss of CYLD contributed to oncogenesis in lung cancer cells." (PMID 27738385, 2016). "Although EGFR-sensitive mutations and other classical lung cancer gene mutations are rare, however, CYLD may be a new therapeutic target for PPLELC." (PMID 34760925, 2021). "Deficiency in either Itch or CYLD will lead to the chronic production of cytokines specifically generated by tumor-associated macrophages, which further contributes to the aggressive growth of lung carcinoma." (PMID 31988639, 2020). "As CYLD normally inhibits the NF‐κB pathway, decreased YTHDC2 expression after CS exposure can promote cancer cell proliferation by modulating the CYLD/NF‐κB axis in CS‐induced lung cancer." (PMID 35560957, 2023). "In LUAD, the overexpression of DC2 regulates CYLD/NF-κB signaling pathway and inhibits the proliferation of lung cancer cells." (PMID 35351856, 2022). "Our previous study revealed that YTHDC2 is a cigarette smoking-drived gene in lung cancer, and it functions as a tumor suppressor through the CYLD/NF-κB signaling pathway, which is mediated by m6A modification." (PMID 36581942, 2022). "Reduced DC2 expression leads to increased lung cancer migration via the CYLD/NF-κB signaling pathway." (PMID 35351856, 2022). "CYLD/NF-κB is a vital downstream pathway that contributes to the tumor-suppressor role of YTHDC2 in lung cancer cells." (PMID 34326699, 2021). "Consistent with YTHDC2, the CYLD mRNA expression in lung cancer tissues was lower than that in normal adjacent tissues in GSE32665 and GSE19188, as well as in GEPIA online tool." (PMID 34326699, 2021). "In order to investigate the clinical significance of CYLD expression, CYLD gene expressions were analyzed in 19 lung carcinoma specimens and the paired paracarcinoma tissues by real-time PCR and western blotting." (PMID 27738385, 2016). "Next, three pairs of CYLD specific siRNAs were designed to knock down the endogenous CYLD in human lung cancer cell lines A549 and H460." (PMID 27738385, 2016). "In the present study, we explored the role of CYLD in human lung cancer specimens and the molecular mechanism of CYLD was investigated in the progression and development of human lung cancers." (PMID 27738385, 2016). "Firstly, we detected the CYLD expression by real-time PCR and western blotting analysis in 39 lung carcinoma specimens and the paired paracarcinoma tissues." (PMID 27738385, 2016). "In order to further identify the function of CYLD in lung carcinoma cells, transient CYLD-knockdown A549 cells were generated using three pairs of siRNA specific to CYLD." (PMID 27738385, 2016). "Conversely, we constructed an expression vector pcDNA3.1(+)-CYLD plasmid and lung cancer cells were transfected with pcDNA3.1(+)-CYLD to increase the levels of CYLD in lung cancer cells." (PMID 27738385, 2016). "Plasmid transfected cells), suggesting that overexpression of CYLD was probably contributed to the cell necrosis in lung cancer cells." (PMID 27738385, 2016). "In conclusion, the results of the present study show that Rig-G inhibits lung cancer cell growth via MiR21/PTEN/Akt and miR181b-1/CYLD-dependent inhibition of NF-κB, which is associated with decreased STAT3 activity." (PMID 27602766, 2016). "All of the results demonstrated that overexpression of CYLD promoted cell death and CYLD played an antitumor activity in the human lung cancer cells." (PMID 27738385, 2016). "The aim of the present study is to investigate the levels of CYLD in lung cancer patients and explore the molecular mechanism of CYLD in the lung cancer pathogenesis." (PMID 27738385, 2016). "The results demonstrated that low levels of CYLD were detected in clinical lung carcinoma specimens." (PMID 27738385, 2016).
lung carcinoma (continued). "Compared to paracarcinoma tissues, the relative CYLD expressions in mRNA levels and protein levels were significantly decreased in lung carcinoma compared to that in the paired paracarcinoma tissues (∗∗p < 0.01)." (PMID 27738385, 2016). "The levels of CYLD were detected in human lung cancer tissues and the paired paracarcinoma tissues by real-time PCR and western blotting analysis." (PMID 27738385, 2016). "Interestingly, the CYLD protein level was also reduced in radiation-resistant lung cancer cells (A549-IR, H358-IR) and radiation-resistant glioma cells (U251-IR) compared to radiation-responsive cancer cells." (PMID 38287022, 2024). "Moreover, the Kaplan-Meier survival analysis revealed that lung cancer patients with high CYLD expression have the better prognosis." (PMID 34326699, 2021). "Its expression in lung cancer cells is low, suggesting that lung cancer cells may downregulate CYLD in order to prevent TNF-α induced apoptosis." (PMID 33262947, 2020). "Knockdown of CYLD promoted cell proliferation of lung cancer cells." (PMID 27738385, 2016). "Three pairs of siRNA were used to knock down the endogenous CYLD in lung cancer cells." (PMID 27738385, 2016). "The aim of the present study is to explore whether and how CYLD regulates cell necrosis in lung cancer cells and further clarifies the molecular mechanism of CYLD in the development of lung cancers." (PMID 27738385, 2016). "All of the data demonstrated that CYLD might work as a tumor suppressor in the progression and development of lung cancer." (PMID 27738385, 2016). "All of the data revealed that overexpression of CYLD promoted cell necrosis in lung cancer cells." (PMID 27738385, 2016). "Moreover, CYLD-overexpressed lung cancer cells were treated with 10 μM of z-VAD-fmk for 12 hours and the result revealed that TNF-α-induced cell necrosis was significantly enhanced." (PMID 27738385, 2016). "We have detected that overexpression of CYLD contributed to cell death of the lung cancer cells." (PMID 27738385, 2016). "Our findings suggested that CYLD was a potential target for the therapy of human lung cancers." (PMID 27738385, 2016). "The result obviously revealed that downregulation of CYLD was observed in lung cancer specimens, and we thought that CYLD might work as a tumor suppressor in cancer development and progression." (PMID 27738385, 2016). "Furthermore, CYLD is a tumor suppressor, and its defects lead to lung cancer metastasis." (PMID 33619866, 2021). "Thus, the reconstitution of CYLD could be an effective and promising method for human lung cancer therapy." (PMID 27738385, 2016). "Knockout of DUSP14, and that of ITCH or CYLD promotes progression of EAE and lung cancer, respectively, accompanied with sustained activation of TAK1 signaling." (PMID 28106845, 2017). "Moreover, several targets of miR-197-3p have been reported in lung cancer cells, including NOXA, Bcl-2-modifying factor (BMF) and lysine 63 deubiquitinase (CYLD)." (PMID 36494333, 2022). "In addition, SOCS3, A20 (TNFIAP3), and CYLD, the transcriptional targets of STAT3 and RelA, were increased in the lung macrophages of mice with lung cancers." (PMID 33539325, 2021). "Additionally, CYLD overexpression can block TRAIL-induced NF-κB activation directly, and consequently increase TRAIL-induced apoptosis in lung cancer cells." (PMID 31988639, 2020). "Notably, CYLD is also downregulated in radiation-resistant NPC, glioma, and lung cancer cells." (PMID 38287022, 2024). "Additionally, Nec-1, the RIP-1 inhibitor, also suppressed the apoptosis rate in TNF-α-induced cell necrosis, but it did not affect the expression of RIP-1 in CYLD-overexpressed lung cancer cells." (PMID 27738385, 2016). "However, the role of CYLD in lung cancer was not clearly clarified." (PMID 27738385, 2016).
spiradenomas (14 papers, 2009 to 2025). "CYLD mutations were also found in 31% (5/16) of the spiradenomas." (PMID 31101826, 2019). "Notably, we find a recurrent missense mutation in the kinase domain of the ALPK1 gene in spiradenomas and spiradenocarcinomas, which is mutually exclusive from mutation of CYLD and can activate the NF-κB pathway in reporter assays." (PMID 31101826, 2019). "Most spiradenomas, however, harbored ALPK1 mutations, which were mutually exclusive from CYLD mutations." (PMID 32461623, 2020).
trichoepithelioma (12 papers, 2009 to 2025). "The discovered variant c.2501dupC (p.Val835SerfsTer52) of the CYLD gene is associated with a structural change in the protein, causes the loss of its function and causes the appearance of multiple trichoepitheliomas in a young woman." (PMID 39403278, 2024). "This study presents a previously undescribed de novo variant c.2501dupC (p.Val835SerfsTer52) of the CYLD gene in a young woman with multiple trichoepitheliomas." (PMID 39403278, 2024). "The new CYLD gene variant p.Val835SerfsTer52 causes the development of multiple familial trichoepitheliomas in BSS and confirms the hypothesis of the association of this gene variant with loss-of-function mutations." (PMID 39403278, 2024). "Familial cylindromatosis, marked by multiple cylindromas, and multiple familial trichoepitheliomas, characterized by numerous trichoepitheliomas without other adnexal tumors, are also recognized as phenotypic variations of CYLD gene defects." (PMID 40342561, 2025).
chronic lymphocytic leukemia (10 papers, 2016 to 2025). "Moreover, ECA has been found to downregulate CYLD in chronic lymphocytic leukemia, and CYLD plays a key role in promoting Treg differentiation and development while maintaining normal T regulatory cell function." (PMID 37047688, 2023). "In addition, many key mediating necrotic apoptosis molecules are downregulated in cancer, such as ubiquitination enzyme CYLD in chronic lymphocytic leukemia (CLL)." (PMID 37878133, 2023). "In addition, the high expression of CYLD have better overall survival in chronic lymphocytic leukemia." (PMID 37549179, 2023). "Similarly, the low levels of RIPK3 and CYLD expression developed chronic lymphocytic leukemia (CLL) cells to resistance from TNF-α/zVAD-induced necroptosis." (PMID 36361505, 2022). "Moreover, alternative splicing of CYLD is detected in many B-cell CLL patients’ samples, which can lead to CD5+ B-cell expansion through sustained NF-κB signaling." (PMID 34454635, 2021). "For example, RIP3 and CYLD are downregulated in chronic lymphocytic leukemia (CLL) because lymphoid enhancer-binding factor 1 (LEF1), which is a transcriptional repressor of CYLD, is upregulated." (PMID 32764483, 2020).
viral infection (10 papers, 2014 to 2023). "CYLD maintains low RIG-I ubiquitination at the resting state, and during viral infection, CYLD is downregulated, allowing K63-linked RIG-I ubiquitination to occur for RIG-I activation." (PMID 35795661, 2022). "About 60% of CYLD+/+ mice survived viral infection, whereas CYLD-/- mice were more sensitive, and only about 20% survived under the same conditions." (PMID 33138315, 2020). "Since IFN-β protects host cells against virus infection, we examined the role of CYLD in restricting HSV-1 infection." (PMID 30388174, 2018). "SDC4 likely promotes redistribution of RIG-I and CYLD in a perinuclear pattern post viral infection, and thus enhances the RIG-I–CYLD interaction and potentiates the K63-linked deubiquitination of RIG-I." (PMID 27279133, 2016). "In addition, membrane fraction assays showed that SDC4, RIG-I and CYLD accumulated at membrane fraction on virus infection." (PMID 27279133, 2016). "In addition, CYLD removes polyubiquitin chains from TBK1 as well as RIG-I, suggesting CYLD is a bona fide negative factor of RIG-I associated innate immune response against viral infection." (PMID 35008917, 2022). "Release of the CYLD-mediated inhibition of TBK1 during this phase results in enhanced IFN/ISG signaling pathway, independently of viral infection." (PMID 25923723, 2015). "Consistently, endogenous CYLD was detected in the SDC4 complex in the absence of viral infection." (PMID 27279133, 2016). "Following virus infection, activation of the RIG/MAVS pathway leads to TBK1 activation (presumably through phosphorylation by an upstream unknown kinase and ubiquitination by the E3 ligases MIB1/2 or Ndrp1) and to the disruption of its interaction with Optn and CYLD." (PMID 25923723, 2015).
glioma (9 papers, 2014 to 2025). A benign or malignant brain and spinal cord tumor that arises from glial cells (astrocytes, oligodendrocytes, ependymal cells). "Around the same time, initial publications began to explore CYLD’s contribution to the pathology of the CNS, particularly in the development of gliomas, which will be discussed further below." (PMID 39945824, 2025). "Proteomic analysis of CYLD-knockdown glioma cells and RNA-seq data from glioblastoma samples revealed the involvement of WNT/β-catenin signaling in the development of the malignant phenotype associated to CYLD depletion." (PMID 39945824, 2025). "Inhibition of this pathway reversed the increased viability observed in CYLD-knockdown glioma cells." (PMID 39945824, 2025). "Glioma subtypes with low CYLD expression are characterized by aggressive features, including reduced survival time, increased proliferation, vascularization, and invasion." (PMID 39945824, 2025). "A key negative regulator of NF-κB signaling is cylindromatosis (CYLD) deubiquitinase and miR-182 is able to directly inhibit the ubiquitin binding of CYLD, a component of the NF-κB signaling pathway, thereby inducing an aggressive phenotype in glioma cells." (PMID 36479040, 2022). "CYLD expression was recently shown to be reduced in gliomas, with an inverse correlation with tumor grade and prognosis." (PMID 25071012, 2014). "In a recent report, gliomas had reduced CYLD expression that was inversely correlated with tumor grade and prognosis." (PMID 25071012, 2014). "Importantly, miR-182 was noted to be overexpressed in gliomas and directly suppressed cylindromatosis (CYLD), an NF-κB-negative regulator." (PMID 26713004, 2015). "Importantly, a recent study reported that CYLD is a direct target of miR-182, the increased expression of which resulted in CYLD reduction and sustained NF-κB activation in gliomas." (PMID 24495516, 2014). "miR-182 also suppresses cylindromatosis (CYLD) to sustain NF-κB activation in glioma." (PMID 24884732, 2014). "Moreover, glioma cells in hypoxic conditions downregulate CYLD expression." (PMID 39945824, 2025).
lymphoma (9 papers, 2016 to 2025). A malignant (clonal) proliferation of B- lymphocytes or T- lymphocytes which involves the lymph nodes, bone marrow and/or extranodal sites. "We tested this hypothesis in lymphomas because of our prior analysis showing that CYLD, IKBKB (encoding IKKβ), and IKBKG (encoding NEMO) are highly co-expressed in hemato-lymphoid cells." (PMID 32024820, 2020). "In our recent studies, A20 promotes the uptake of lymphoma cells by dendritic cells from non-Hodgkin lymphoma, whereas CYLD stimulates macrophage phagocytosis in acute myeloid leukemia." (PMID 40896706, 2025). "The evidences suggest the effects of CYLD in negatively regulating functions of leukemic cells rather that lymphoma cells." (PMID 40896706, 2025). "In line with the primary lymphoma cases, we observed variable levels of CYLD mRNA expression in DLBCL and MCL cell lines." (PMID 36922488, 2023). "Using a retroviral overexpression system, we expressed either wild type CYLD or CYLD R324A in a panel of lymphoma cell lines." (PMID 36922488, 2023). "Apoptosis appears to be the dominant type of cell death induced following reactivation of CYLD in the lymphoma cell lines examined." (PMID 32024820, 2020). "Collectively, our findings demonstrate that loss of CYLD renders BCR-dependent lymphoma cell lines less sensitive to BCR pathway inhibition by ibrutinib and sotrastaurin, indicating that their inhibitory effects on proliferation and signaling are at least partially dependent upon CYLD." (PMID 36922488, 2023). "Besides, CYLD acted as a crucial regulator of Adult T-cell leukemia/lymphoma (ATLL) survival." (PMID 33842368, 2021). "Ectopic overexpression of WT CYLD or a MALT1-cleavage resistant mutant of CYLD reduced NF-κB activity and growth of BCR-dependent lymphoma cell lines." (PMID 36922488, 2023). "This is in accordance with our findings showing that silencing of CYLD promotes NF-κB activation and cell growth and, conversely, ectopic expression of CYLD represses NF-κB signaling and cell growth in BCR-dependent lymphoma cell lines." (PMID 36922488, 2023). "In lymphoma cells, knockout of GRK2 leads to enhanced MALT1-mediated IκB phosphorylation, RELB and CYLD cleavage, cytokine secretion, and cell proliferation, and GRK2 rescue reverses these effects." (PMID 34917606, 2021). "In lymphoma like CLL, CYLD protein expression levels was lower in tumor invasive lymph node than in normal lymph node samples." (PMID 33827598, 2021). "Ectopic overexpression of WT CYLD or a MALT1-cleavage resistant mutant of CYLD reduced phosphorylation of IκBα, repressed transcription of canonical NF-κB target genes and impaired growth of BCR-dependent lymphoma cell lines." (PMID 36922488, 2023). "While posttranslational mechanisms that prevent CYLD and RIPK1 from becoming death-signaling molecules in the early death checkpoint are crucial to lymphoma cell survival, the induction of NFκB-dependent prosurvival genes in the late checkpoint is also integral and this has been widely studied." (PMID 32024820, 2020). "To assess whether MALT1-mediated CYLD cleavage directly contributes to growth of BCR-dependent lymphoma cell lines, we generated a CYLD mutant that can no longer be cleaved by MALT1 (CYLD R324 A)." (PMID 36922488, 2023). "Furthermore, silencing of CYLD expression rendered BCR-dependent lymphoma cell lines less sensitive to inhibition of NF-κΒ signaling and cell proliferation by BCR pathway inhibitors, e.g., the BTK inhibitor ibrutinib, indicating that these effects are partially mediated by CYLD." (PMID 36922488, 2023). "Since differences in MALT1 protein expression do not account for the observed differences in cleaved CYLD levels, this suggests that post-translational regulation of MALT1 activity, not MALT1 expression as such, determines CYLD cleavage in lymphoma cell lines." (PMID 36922488, 2023). "In the future, we will further investigate the deubiquitinase function of CYLD in non-GCB-DLBCL and in different types of lymphoma." (PMID 33827598, 2021).
lymphoma (continued). "Our study indicated that there was no significant change in NFκB activity in both lymphoma cell lines with CYLD knockout (OCI-Ly10 and HBL-1) after BTK inhibitor treatment, suggesting that BTKis down-regulated NFκB activity is dependent on the CYLD pathway." (PMID 33827598, 2021).
pancreatic cancer (8 papers, 2014 to 2022). "Takiuchi reported that miR-181 decreased the sensitivity of pancreatic cancer cell to gemcitabine through activating NF-κB by CYLD inhibition." (PMID 26043084, 2015).